BDNF (brain derived neurotrophic factor)
Diseases named in the same sentence as BDNF in open-access papers (continued):
Sharing a sentence is not in itself a finding about the gene and the disease.
depression (continued). "TrkB, a receptor of BDNF, triggers cascades of downstream signaling transduction to modulate neurogenesis in the pathogenesis of depression." (PMID 38273824, 2023). "Multiple studies and meta-analyses have found that people with depression had reduced BDNF levels in their blood, along with lower ghrelin levels." (PMID 37764744, 2023). "While functional neuroplasticity cannot be directly tested in the living human brain, post-mortem studies of depression show reductions in markers of neuroplasticity, including reduced BDNF and decreased synapses and synapse-related gene expression." (PMID 37160885, 2023). "The injection of BDNF in the hippocampus decreased depression-like behavior, while the deletion of TrkB in the dentate gyrus or the inhibition of TrkB signaling blocked the effects of antidepressants on behavior." (PMID 37895171, 2023). "Since the sample size was measured using the primary outcome, depression severity, it was possible that the number of patients was insufficient to show changes in serum BDNF." (PMID 38107143, 2023). "the brain-derived neurotrophic factor, is inhibited, neurotransmitters are disrupted; the grounds for MH disorders (i.e., depression) are provided." (PMID 36609286, 2023). "Previous studies have observed a decrease in plasma and serum BDNF levels in patients with depression, bipolar disorder, and eating disorders and increases after treatment for these disorders." (PMID 37822121, 2023). "Expression of the brain-derived neurotrophic factor is also diminished in patients with impaired functions in the hippocampus, prefrontal cortex, and other depression-related brain regions." (PMID 36979291, 2023). "Using the cell line, we screened for substances that upregulate BDNF level to identify prophylactic and therapeutic agents against depression." (PMID 38082356, 2023). "Rats subjected to unpredictable chronic mild stress (UCMS) display behavioral defects akin to those of depression, and this is accompanied by reduced BDNF concentrations in the CA1 and CA3 regions of the hippocampus and also the PFC." (PMID 37174977, 2023). "Numerous studies have shown that BDNF is the most abundant neurotrophic factor in brain, which is involved in the pathophysiology and treatment of depression." (PMID 37408379, 2023). "Serum BDNF levels correlate with hippocampal volume, and insufficient BDNF levels can impair neurogenesis and lead to the onset of depression." (PMID 37139495, 2023). "Lactobacillus reuteri and Bifidobacterium Teenis administration improved BDNF production in the hippocampus of mice with anxiety/depression and colitis." (PMID 37686011, 2023). "BDNF’s role in the pathophysiology of depression is well known, and lower serum levels of the factor were found in people with major depressive disorders compared to HCs." (PMID 36979300, 2023). "As such, it can be said that a reduced production of BDNF and neuroplasticity can lead to depression." (PMID 36767702, 2023). "Decreased BDNF concentrations has been evidenced in many neurodegenerative and psychiatric conditions in adults, such as Alzheimer dementia, major depressive disorder, multiple sclerosis, Parkinson disease and autism spectrum disorder." (PMID 37548699, 2023). "Inversely, upregulation of the BDNF/TrkB signaling pathway exerted anti-depression effects on chronic restraint-stress-induced depression." (PMID 37168717, 2023). "Stress-induced depression and anxiety (DA) are closely connected to gastrointestinal inflammation and dysbiosis, which can suppress brain-derived neurotrophic factor (BDNF) in the brain." (PMID 37299451, 2023). "Panax ginseng extract improves depression-like behavior in rats primarily by promoting hippocampal neurogenesis and the BDNF-TrkB signaling pathway." (PMID 37836833, 2023).
depression (continued). "Our previous studies have demonstrated that SNS delivers anti-depressive effects by regulating hippocampal synaptic plasticity, mitochondrial function, and brain-derived neurotrophic factor content in a rat depression model." (PMID 38026979, 2023). "Bidari and colleagues reported that a one-month treatment with duloxetine significantly reduced serum BDNF levels, even after adjusting for depression, pain, and severity of the disease in their linear mixed model (p < 0.01)." (PMID 38127937, 2023). "The decreased BDNF can be found in patients with depression, whereas antidepressant treatment can increase the levels of BDNF." (PMID 37139495, 2023). "Serotonin and BDNF both contribute to synaptic regulation and structural changes in the brain, which are important in mood disorders such as depression." (PMID 37631295, 2023). "BDNF, as a protective biomarker for depression, was shown to be a significant predictor for survival in patients with CAD and CKD." (PMID 38275390, 2023). "Animal studies have shown that it can improve depression-like behaviours in rats by reversing changes in the expression of brain-derived neurotrophic factor (BDNF) and its receptor induced by chronic stress." (PMID 37386630, 2023). "A previous study showed that hippocampal atrophy is accompanied by decreased BDNF expression in patients with depression." (PMID 37513692, 2023). "Although mounting evidence implicates the potential of BDNF to be used as a biomarker in depression, the studies on BDNF peripheral level in the population of children and adolescents with depression are scarce and inconclusive." (PMID 34590201, 2023). "Many previous studies have reported an association between brain-derived neurotrophic factor (BDNF) and psychiatric disorders such as depression and suicide in the adult population." (PMID 36517640, 2023). "The BDNF-TrkB signaling pathway, as well as the downstream kinases Akt and ERK and the mTOR pathway, have been implicated in depression and neuroplasticity." (PMID 37047730, 2023). "Another preclinical study found that histone methylation was not reversed by treatment with antidepressants and that chronic imipramine induced long-lasting H3 hyperacetylation at the BDNF P3 and P4 promoters in the social defeat model of depression." (PMID 37592949, 2023). "Another study with behavioral tests demonstrated antidepressant effects as well as an elevation in serum BDNF levels following the prolonged use of allopurinol, recently correlated with its effects on serotonin and depression-like behaviors." (PMID 37631295, 2023). "A meta-analysis of circulating BDNF levels in depression revealed lower levels of BDNF in depressed patients compared with controls." (PMID 36787304, 2023). "The interplay of oxidative stress, HPA axis imbalance, serotonergic pathways, and BDNF plays a significant role in the development and progression of depression and other neuropsychiatric disorders." (PMID 37631295, 2023). "Folic acid, also known as vitamin B9, can potentially increase the levels of 5-HT and improve the expression of BDNF and glutamate receptor 1 (GluR1) in the brains of rats with depression." (PMID 37686011, 2023). "Evidence shows that the brain-derived neurotrophic factor (BDNF) is an important biomarker for the pathogenesis of depression." (PMID 37592005, 2023). "In people with depression, BDNF expression is decreased in the limbic area of the brain due to neuronal atrophy." (PMID 36978872, 2023). "One of these lines of research, considering neurotrophic factors, have studied the role of brain-derived neurotrophic factor (BDNF) in the neurobiology of major depression." (PMID 37834258, 2023). "(2015) reported that at baseline, serum and plasma BDNF levels were reduced in these patients with major depressive disorder and bipolar disorder compared to healthy controls." (PMID 36722793, 2023).
depression (continued). "Nevertheless, the normalization of BDNF levels plays a significant role in promoting synaptic plasticity, enhancing neuronal repair, and mitigating depression symptoms." (PMID 38026940, 2023). "In another study, the level of mature BDNF in serum-derived sEV was found to be decreased and pro-BDNF increased in patients with Major Depression (MD) compared to controls." (PMID 38435713, 2023). "Herein, we construct the quercetin-based alginate nanogels (quercetin nanogels) loaded with BDNF (BDNF-quercetin nanogels) composed of thermosensitive gel for the combination therapy of depression by intranasal delivery." (PMID 37848975, 2023). "This review article described altered BDNF in schizophrenia, depression and animal models, as well as the effects of antipsychotic and antidepressive treatments on the expression of BDNF." (PMID 37077958, 2023). "In contrast, it was observed that iron overload inhibited BDNF expression in the hippocampus, leading to direct damage to synapses and the manifestation of depression-like behaviours." (PMID 37735410, 2023). "Research indicates that the expression of CREB and BDNF in depression models is reduced compared with control groups, and these changes can be reversed by administration of the NMDA receptor antagonist memantine." (PMID 36819781, 2023). "In mice, researchers found that Lactobacillus-derived EVs can change the expression of BDNF in the hippocampus and exert antidepressant-like effects in stress-induced depression model mice." (PMID 36970289, 2023). "The administration of psychobiotics showed increased BDNF levels and lower depression scores post-intervention, suggesting that probiotics have an effect in increasing BDNF levels, which modulates depressive symptoms." (PMID 37448433, 2023). "NMDA‐R modulators cause fast antidepressant impacts and increase BDNF expression, implicating NMDA‐R dysregulation in depression." (PMID 37032465, 2023). "With growing evidence in rodent models for a role of BDNF in synaptic plasticity in the adult CNS, attention progressively focused on the possible role of BDNF/TrkB signalling in mood disorders and especially depression." (PMID 37470055, 2023). "BDNF plays a critical role in depression and anxiety, and antidepressants exert their effects by activating BDNF-tropomyosin receptor kinase B (TrkB) signaling." (PMID 37533986, 2023). "Previous studies suggested that the expression levels of BDNF and inflammatory cytokines in the peripheral blood are related to the degree of depression and cognitive impairment of patients." (PMID 37168717, 2023). "P2X4R and P2X7R are involved in neuropathic pain, intracerebral hemorrhage, and depression by regulating BDNF actions." (PMID 35821455, 2023). "The present study was the first double‐blind placebo‐controlled clinical trial assessing the effects of hesperidin on the severity of depression, serum cortisol, and BDNF levels in post‐CABG patients." (PMID 38107143, 2023). "BDNF, a crucial biomarker for the pathogenesis of depression, is also a valuable measure of the difference between healthy and depressed individuals." (PMID 37848975, 2023). "Nevertheless, the reports about the effects of BDNF on depression and anxiety are controversial, as increased BDNF levels were shown to produce a anxiety-like or depression-like phenotype." (PMID 37895171, 2023). "In human, one study involving patients with depression found that higher TSH levels were associated with lower serum BDNF levels and a smaller increase in BDNF during antidepressive treatment." (PMID 38130289, 2023). "Clinical and preclinical studies demonstrated that some antidepressants alleviated depression by activating TrkB and BDNF." (PMID 37408379, 2023). "A reduced expression of brain-derived neurotrophic factor (BDNF) is exhibited in depression and has been found to be dysregulated in PTSD/traumatic brain injury (TBI) in veterans." (PMID 38455905, 2023).
depression (continued). "The BDNF-TrkB pathway is involved in the development of epilepsy, depression, Alzheimer’s disease, and other diseases." (PMID 37884604, 2023). "Purinergic receptors (A1, A2A, A2B, P2X4, P2X7, P2Y11Rs) have been recognized as important mediators of BDNF activation and participate in multiple pathologies, including stroke, neuropathic pain, and depression." (PMID 35821455, 2023). "Alzheimer's disease, depression, schizophrenia, and other cognitive diseases are only a few of the neurological and psychiatric conditions for which BDNF gene alterations have been researched." (PMID 38015338, 2023). "Researchers have shown that ginsenoside Rb1, via the miR-134-mediated BDNF signaling pathway, regulates hippocampal synaptic plasticity to improve depression symptoms." (PMID 38249586, 2023). "It is well-acknowledged that stress contributes to the pathophysiology of depression and shows adaptive adjustments in many pathways, including brain-derived neurotrophic factor (BDNF), inflammatory cytokines, and the spleen, to promote resilience." (PMID 37111321, 2023). "The relevance of BDNF in depression is further supported by studies demonstrating that antidepressant drugs are associated with a reversal of hippocampal atrophy and contemporary increases in BDNF expression levels." (PMID 36766691, 2023). "In postmortem studies of brain tissue, particularly from the hippocampus and amygdala, levels of BDNF mRNA and protein were reduced in people with depression." (PMID 36831706, 2023). "Previous in vivo studies have extensively explored BDNF effects in different diseases, including schizophrenia and depression." (PMID 38050515, 2023). "Anxiety-like and depression-like behaviors, the concentrations of brain-derived neurotrophic factor (BDNF), malondialdehyde (MDA), and ferric reducing ability of plasma (FRAP) were evaluated." (PMID 39484298, 2023). "The experimental results also showed that A. muciniphila alleviated as the symptoms of depression by influencing the levels of monoamine neurotransmitters and BDNF." (PMID 37492530, 2023). "Increasing reports show anti‐depression drugs elevate BDNF expression in resistance to neuroinflammation‐induced depression." (PMID 36550591, 2023). "Conversely, in animals displaying a stress-induced depression-like phenotype, a single bilateral infusion of BDNF in the HC mimics the normalization of the depression-like behavior elicited by antidepressant drugs." (PMID 37298449, 2023). "Preclinical and clinical studies have consistently shown that levels of BDNF decrease within the brain during periods of emotional and psychological stress and depression." (PMID 37599890, 2023). "Neurotrophins are intertwined with other depression-related pathways: BDNF is a downstream target of the monoamine signaling cascade (cf. “The monoamine theory”)." (PMID 36203007, 2023). "BDNF is a neurotrophin involved in synaptic plasticity, extensively studied in the context of depression." (PMID 36830028, 2023). "Similar findings were reported from human studies, with several studies of depression observing an attenuated BDNF methylation change after receiving antidepressant treatment." (PMID 36911114, 2023). "Overall, this investigation revealed that engeletin produces antidepressant‐like properties in mouse depression models, promoting synaptic plasticity by upregulating the PFCs' BDNF‐TrkB‐mTORC1 signalling pathway." (PMID 37799103, 2023). "The same inverse relationship can be interpreted from the mir-132 and BDNF relation in depression disorder." (PMID 37396946, 2023). "Further omics analysis and protein verification revealed that the treatment of BDNF-Quercetin nanogels on depressive disorder was mainly related to the glutamatergic system, PI3K-Akt, and BDNF-TrkB signaling pathway." (PMID 37848975, 2023). "Preclinical studies also revealed BDNF downregulation in the brains of MDD model mice, and BDNF played a critical role in the onset and/or development of depression." (PMID 37007014, 2023).
depression (continued). "In this study, we provide a promising strategy for brain delivery of BDNF for treating depressive disorders, effectively achieved through combining quercetin nanogels and intranasal administration." (PMID 37848975, 2023). "BDNF was mainly produced from astrocyte whose elevation contributed to the improvement of depressive disorder." (PMID 36550591, 2023). "Many studies have suggested that the BDNF level in the peripheral blood is decreased in patients with schizophrenia or severe depressive disorder." (PMID 37013544, 2023). "Eight SNPs were identified as associated with depressive disorder and belonged to the ANK3, BDNF, CACNA1C, and GRID1 genotypes, with the majority belonging to the ANK3 and CACNA1C genotypes." (PMID 38012695, 2023). "In a previous study, 30-day treatment with paeoniflorin (20 mg/kg, i.p.)was shown to reverse CUS-induced depression-like behaviors in mice by increasing BDNF and postsynaptic density protein 95 (PSD-95) expression and dendritic spine density." (PMID 36046834, 2022). "EA improves CUMS-induced depression-like behavior by regulating BDNF and 5-HT levels and suppressing the secretion of proinflammatory serum cytokines." (PMID 36014776, 2022). "An important role in the pathophysiology of depression stems from the 5-HT involving hippocampal brain-derived neurotrophic factor (BDNF) expression signaling mechanism." (PMID 36078738, 2022). "Our study revealed that some plants and their derivatives target BDNF, other pharmacological targets, or the gut microbiota to relieve depression in different experimental models." (PMID 36499295, 2022). "Given many studies which found lower BDNF levels in the serum and CSF of the patients with depression, this question is raised: how does BDNF level change in the patients with chronic pain, including FM with or without depression?" (PMID 35501732, 2022). "For instance, garlic essential oil showed an anti-depressive effect against CUMS-induced depression via upregulating the expression levels of hippocampal BDNF, cyclic adenosine monophosphate response element-binding protein (CREB), and protein kinase B." (PMID 36358502, 2022). "One of the current explanations for why physical exercise can effectively relieve people’s anxiety and depression symptoms was that exercise can promote the increase in brain-derived neurotrophic factor (BDNF)." (PMID 35323380, 2022). "Moderate physical exercise for 6 weeks is sufficient to reduce self-reported depression levels and increase peripheral BDNF and NGF levels in postmenopausal woman." (PMID 36233029, 2022). "For example, social stress lowers BDNF and glutathione reductase levels, leading to oxidative stress-induced anxiety/depression-like behaviors in rats." (PMID 36761172, 2022). "Numerous studies have found an association between neurotrophic growth factors, particularly BDNF, and depression." (PMID 36217471, 2022). "Many studies have shown that the mRNA and protein levels of serum BDNF in patients with depression and PD were significantly reduced." (PMID 36158555, 2022). "Due to its anti-inflammatory properties, SBH can also regulate BDNF, hence alleviating depression symptoms." (PMID 36014336, 2022). "We were therefore unable to replicate a correlation between altered BDNF methylation and childhood trauma/depression." (PMID 34989854, 2022). "These decreases in serum BDNF levels have been correlated with cognitive impairment, depression, and restless legs syndrome (RLS)." (PMID 35743271, 2022). "Remarkably, selective serotonin reuptake inhibitor (SSRI) antidepressants have been reported to increase serum concentrations of BDNF in patients suffering from major depressive disorder and contribute to improvements in the symptoms." (PMID 35406124, 2022). "For this, the evolution process of research hotspots on the role of BDNF in depression was evaluated." (PMID 36291673, 2022).